ENSG00000199959
Synonyms: LOC124904808
Gene: Small nucleolar RNA gene on chromosome 1 (84,277,321 to 84,277,457, forward strand). Ensembl gene ENSG00000199959.
Gene Ontology:
Biological process: RNA processing
Cellular component: nucleolus
Homologues: Orthologues: rat Gm22806 (86% identical), rat LOC120101251 (86% identical), mouse Gm22353 (85% identical), mouse Gm22806 (84% identical), mouse Gm22683 (83% identical), mouse Gm25896 (82% identical), mouse Gm24166 (81% identical), mouse Gm55799 (60% identical). Paralogues in human: SNORA2B (91% identical), SNORA2C (71% identical), SNORA2A (67% identical).